NPAS2 (neuronal PAS domain protein 2)
Diseases named in the same sentence as NPAS2 in open-access papers (continued):
Sharing a sentence is not in itself a finding about the gene and the disease.
vitamin D deficiency (2 papers, 2011 to 2017). A nutritional condition produced by a deficiency of VITAMIN D in the diet, insufficient production of vitamin D in the skin, inadequate absorption of vitamin D from the diet, or abnormal conversion of vitamin D to its bioactive metabolites. "A large co-expression network containing Npas2, Bmal1, and Vdr was observed to form with the Ti biomaterials, which was disintegrated by vitamin D deficiency." (PMID 28817668, 2017). "The primary molecular target of NPAS2 is Per2, which was also found to be significantly modulated by vitamin D deficiency in the peri-implant tissue." (PMID 21264318, 2011). "On the contrary, the cluster containing Per2 was upregulated by vitamin D deficiency and showed a complementary expression pattern to the NPAS2 cluster." (PMID 21264318, 2011). "Initially, we anticipated finding genes that were involved in the classic category of bone remodeling; however, in two-way ANOVA, we found NPAS2 as the most significantly affected gene by vitamin D deficiency in the peri-implant tissue." (PMID 21264318, 2011). "Among the VD-deficiency altered-gene list, we found Neuronal PAS domain 2 (NPAS2) and Period Homolog 2 (Per2) as the most significantly affected genes by vitamin D deficiency in the peri-implant tissue." (PMID 21264318, 2011). "The hierarchical clustering re-evaluated by directionality indicated that upregulated NPAS2 and cartilage ECM genes by the implant placement were completely attenuated by vitamin D deficiency." (PMID 21264318, 2011). "NPAS2 and Aryl hydrocarbon receptor nuclear translocator-like (ARNTL/Bmal 1) were upregulated around implant and diminished by vitamin D deficiency, whereas the expression pattern of Per2 was complementary." (PMID 21264318, 2011).
aging (1 paper, 2017). A developmental process that is a deterioration and loss of function over time. "Our data showed associations between cognitive aging and single nucleotide polymorphisms (SNPs) in 4 key circadian clock genes, CLOCK rs3749473 (p = 0.0017), NPAS2 rs17655330 (p = 0.0013), RORA rs13329238 (p = 0.0009), and RORB rs10781247 (p = 7.9 × 10−5)." (PMID 28412756, 2017).
arthropathy (1 paper, 2010). Any disorder of the joints. "In agreement with functional redundancy of NPAS2 and CLOCK, only double deficiency of CLOCK and NPAS2 in mice results in arthropathy (E.A. Yu and D.R. Weaver, personal communication) similar to arthropathy developed upon BMAL1 deficiency CLOCK is the major interacting partner of BMAL1." (PMID 21149897, 2010).
asthma (1 paper, 2018). "In this study, several genes including Gdpd2, Spon2, Pon1, Scgb3a2, Ighv2-3, Sult1d1, Cyp2f2, Npas2, Arntl, and Igkv4-68 were down-regulated in OVA-challenged mice compared with control mice, may be useful as biomarkers of asthma." (PMID 29086354, 2018).
cerebrovascular diseases (1 paper, 2023). "All this evidence highlights a particular role of NPAS2 in the pathogenesis of coronary artery disease and cerebrovascular diseases." (PMID 37887064, 2023). "Dysregulation of NPAS2 can lead to disruptions in circadian rhythms and may contribute to sleep disturbances, psychiatric disorders and other health issues, such as neoplastic, cardiovascular and cerebrovascular diseases." (PMID 37887064, 2023).
chronic fatigue syndrome (1 paper, 2021). "Gene variants of NPAS2 are related to winter depression, reproduction and seasonal changes, and chronic fatigue syndrome." (PMID 34460437, 2021).
dementia (1 paper, 2023). Loss of intellectual abilities interfering with an individual's social and occupational functions. "NPAS2, whose levels were decreased in the patient-derived cells, is a circadian rhythm gene, a system that has been linked to many diseases including dementia." (PMID 37566069, 2023).
dependence (1 paper, 2022). "Together, these results suggest that tolerance, physical dependence and opioid‐induced hypersensitivity behaviors could be modulated by NPAS2 signaling in a sex specific manner." (PMID 36053258, 2022). "However, the role of NPAS2 in opioid tolerance and dependence had yet to be established." (PMID 36053258, 2022).
esophageal cancer (1 paper, 2016). A primary or metastatic malignant neoplasm involving the esophagus. "The esophageal cancer cells were negatively isolated by MACS and subjected to RT-qPCR to detect the expression of circadian clock molecule mRNA, including NFIL3, Per1, Per2, Bmal1, Cry1, Cry2, Clock and Npas2." (PMID 26898709, 2016).
fibrosis (1 paper, 2022). the formation of excess fibrous connective tissue in an organ or tissue in a reparative or reactive process. "In one study, NPAS2 was found to show high expression in a human fibrosis specimen and in a mouse fibrosis model." (PMID 35983515, 2022).
Infertility (1 paper, 2022). "This search revealed that in the case of NANOS1 overexpression, three infertility related genes (CREBBP, CCNB1, and NPAS2) and five cancer-germ cell genes (CENPL, ERCC6L, KIF18A, SIAH1, and TRIM71) were present in three clusters." (PMID 35743036, 2022).
insomnia (1 paper, 2022). A sleep disorder characterized by difficulty in falling asleep and/or remaining asleep. "Polymorphisms in clock genes have also been associated with MDD including Cry1 and Npas2 and a Clock gene polymorphism was associated with insomnia and relapse in people with MDD." (PMID 36161151, 2022).
leiomyosarcoma (1 paper, 2018). An uncommon, aggressive malignant smooth muscle neoplasm, usually occurring in post-menopausal women. "The minor allele (A) of NPAS2 rs895520 was associated with an increased predisposition to sarcoma of 33% and leiomyosarcoma of 44%." (PMID 30518396, 2018). "Employing an additive model of inheritance CLOCK rs1801260 and PER2 rs934945 were statistically significantly associated with liposarcoma, while NPAS2 rs895520 and RORA rs339972 were statistically significantly associated with leiomyosarcoma." (PMID 30518396, 2018).
lymph node metastasis (1 paper, 2022). "In addition, genetic variants in the NPAS2 gene are associated with large tumor size, lymph node metastasis, and a poorer prognosis." (PMID 36118525, 2022).
malignant glioma (1 paper, 2022). A grade III or grade IV glioma arising from the central nervous system. "The eleven genes within the circadian rhythm pathway (AC020907.1, Y_RNA, TMEM72‐AS1, KRT16P2, DLX6‐AS1, AP002414.1, hsa‐miR‐424, TBPL1, NPAS2, CRY2, and ETNK1) were used to construct a model to evaluate the importance of these genes in malignant glioma." (PMID 35194922, 2022). "During the process of illustrating the circadian rhythm pathway, among the 6 coding genes, we exhibited the biological functions of TBPL1, NPAS2, CRY2, and ETNK1; therefore, what are the roles of VPS33B and C9ORF40 in malignant glioma?" (PMID 35194922, 2022). "Since all three pathways act through AC020907.1, Y_RNA, TMEM72‐AS1, KRT16P2, DLX6‐AS1, AP002414.1, hsa‐miR‐424, TBPL1, NPAS2, and CRY2, these genes could serve as potential therapeutic targets for malignant glioma." (PMID 35194922, 2022). "Fourteen genes within the cellular senescence pathway (AC020907.1, Y_RNA, TMEM72‐AS1, KRT16P2, DLX6‐AS1, AP002414.1, hsa‐miR‐424, TBPL1, NPAS2, CRY2, C9ORF40, AL136115.1, AC102941.1, and AC008738.2) were used to construct a model to evaluate the importance of these genes in malignant glioma." (PMID 35194922, 2022). "Fourteen genes within the tumour immune microenvironment pathway (AC020907.1, Y_RNA, TMEM72‐AS1, KRT16P2, DLX6‐AS1, AP002414.1, hsa‐miR‐424, TBPL1, NPAS2, CRY2, VPS33B, CT62, DPY19L2P1, and KCNH1‐IT1) were used to construct a model to evaluate the importance of these genes in malignant glioma." (PMID 35194922, 2022).
memory impairment (1 paper, 2025). "The data suggest that a role for peripheral NPAS2 in constant light-induced memory impairment in females, and potential mediation by altered cortical circadian Clock gene expression, merit further investigation." (PMID 40069567, 2025).
mucopolysaccharidosis type 2 (1 paper, 2013). A lysosomal storage disease leading to a massive accumulation of glycosaminoglycans and a wide variety of symptoms including distinctive coarse facial features, short stature, cardio-respiratory involvement and skeletal abnormalities. "ARNTL, the heterodimerization partner of CLOCK and NPAS2, enhances their enzymatic function, and the decreased expression of these central components of the molecular clock could hinder the correct clock gene expression in the fibroblasts of Mucopolysaccharidosis type II patients." (PMID 24083598, 2013).
non-alcoholic fatty liver disease (1 paper, 2021). "NPAS2 was closely associated with fetal liver metabolism and non-alcoholic fatty liver disease." (PMID 34460437, 2021).
pancreatic cancers (1 paper, 2023). "Previous studies have identified many polymorphisms affecting multiple clock genes (BMAL1, CLOCK and NPAS2) that are linked to increased risks in prostate, breast, ovarian and pancreatic cancers." (PMID 36978001, 2023).
prion disease (1 paper, 2023). A transmissible disease that is caused by a protein that is able to induce abnormal folding of normal cellular proteins, leading to characteristic spongiform brain changes, which are associated with neuronal loss without an inflammatory response. "Interestingly, NPAS2 has also been implicated in prion diseases and is a regulator of genes controlling inflammation in AD." (PMID 37566069, 2023).
prostate tumor (1 paper, 2023). "Afterwards, we took advantage of the TCGA and GEO databases and found that prostate tumors express significantly higher levels of NPAS2 mRNA than in adjacent normal tissues and benign prostate samples." (PMID 36978001, 2023). "With the aim of investigating the effects of NPAS2 on prostate tumor growth in vivo, we subjected the PC-3 cells with a stable NPAS2 knockdown to nude mice, these tumor cells formed a relatively obvious tumor cell mass." (PMID 36978001, 2023).
sarcopenia (1 paper, 2025). Progressive decline in muscle mass due to aging which results in decreased functional capacity of muscles. "However, the causality of the association between the circadian timing system of the liver and sarcopenia variables was not demonstrated, and the effects included both gene upregulation (Per, Cry, Nr1d1, Nr1d2, and Dbp) and downregulation (Bmal1 and Npas2)." (PMID 39747789, 2025).
sleep disorder (1 paper, 2023). A change from the patient's baseline sleeping pattern, in the hours slept and/or an alteration/dysfunction in the stages of sleep. "For instance, NPAS2, which is involved in the circadian rhythm, has a splicing disorder in its transcripts that may be related to sleep disorder in AD." (PMID 37799732, 2023).
tumor (48 papers, 2009 to 2025). "The reason we chose NPAS2 for validation is that NPAS2 was only significantly elevated in tumor but associated with poor prognosis." (PMID 37155150, 2023). "The pathway-based analysis further revealed that four tumor suppressor genes (Per2, Prkaa2, Npas2, Arntl) were associated with circadian rhythm pathway." (PMID 31523185, 2019). "The formation of heterodimers between Npas2 and Arntl (Bmal1) may regulate the transcription of tumor cell growth and survival, further indicating a potential tumor-suppressing effect associated with these genes." (PMID 35457963, 2022). "Moreover, another core circadian gene BMAL1 was also found to be associated with the NPAS2-mediated tumor cell survival in HCC." (PMID 28333141, 2017). "KEGG analysis demonstrated that circadian rhythm pathway was significantly enriched on both 3 d and 7 d, genes related to disease/tumor, including Tns4 and Neu1 (upregulated), as well as Npas2 and Cry1 (downregulated), exhibited obvious changes." (PMID 39727670, 2025). "Neuronal PAS Domain Protein 2 (NPAS2) is a core circadian clock gene that not only regulates biological rhythms but also plays a significant role in tumor progression." (PMID 40710178, 2025). "The expression of NPAS2 was significantly lower in tumor samples when compared to normal samples in LUAD, LUSC, KIRP, and LIHC." (PMID 38291048, 2024). "The expression of NPAS2 mRNA in tumor and normal tissues was first compared in TCGA pan-cancer datasets." (PMID 38291048, 2024). "Further IHC staining confirmed that NPAS2 was down-expressing in the tumor tissues of NPAS2 knockdown group." (PMID 37120564, 2023). "NPAS2 is regarded as a promising predictor of clinical outcomes in various malignancies and was reported to behave as a tumor suppressor in colorectal carcinogenesis." (PMID 37887064, 2023). "Among genito-urinary tract malignant neoplasms, NPAS2 expression patterns in prostate neoplasia suggested a tumor-suppressor function and showed significant correlation with the immune components of the tumor microenvironment." (PMID 37887064, 2023). "NPAS2 knockdown inhibited cell proliferation and promoted cell apoptosis in vitro and suppressed tumor growth in a nude mouse model in vivo." (PMID 36978001, 2023). "As we expected, we found that NPAS2 knockdown significantly inhibited tumor growth, and the tumor volume and weight of the NPAS2 knockdown group were notably smaller than the NC group." (PMID 37120564, 2023). "Compared with the shCtrl group, the NPAS2 knockdown nude mice showed a significant reduction in tumor volumes and tumor weights." (PMID 36978001, 2023). "We then identified which immune cells subtypes present in the tumor infiltration were associated with the expression of the three CCGs, PER-1, CRY2, and NPAS2 and the prognosis of HCC." (PMID 36118525, 2022). "Npas2, also known as neuronal PAS domain protein 2, is also recognized as a tumor suppressor, It has been shown that Npas2, as one of the core circadian rhythm genes, can play a role in cell development by regulating DNA-related genes." (PMID 35983515, 2022). "Npas2 had been shown to bind to the c-Mycpromoter and suppress its transcription and lower expression of Npas2 resulted in increased cell growth and cycle progression of tumor cells." (PMID 32437452, 2020). "NPAS2 is suggested to be a putative tumour suppressor playing an important role in transcriptional suppression of the protooncogene c-Myc, DNA damage response, and cell cycle control by regulating diverse downstream genes." (PMID 30996687, 2019). "Quantitative reverse transcription-PCR (qRT)-PCR and western blot analyses showed that NPAS2 was significantly upregulated in HCC tumor tissues at both mRNA and protein levels when compared with paired nontumor tissues." (PMID 28333141, 2017). "Taken together, these results show that NPAS2 promotes tumor growth in vivo by inducing cell proliferation and inhibiting cell apoptosis." (PMID 28333141, 2017).
tumor (continued). "In the breast, PER and CRY are associated with better prognosis in ER+/HER2– tumours, yet CLOCK and NPAS2 are linked to better prognosis in the more aggressive ER–/HER2– tumours." (PMID 27590298, 2016). "NPAS2 (neuronal PAS domain protein 2) is a circadian gene as well as a putative tumor suppressor involved in DNA damage response." (PMID 20015385, 2009). "Furthermore, RT-qPCR analysis performed on tumor and normal tissues obtained from our clinical facility confirmed a significant elevation of NPAS2 expression levels in the tumors from LUAD patients." (PMID 38291048, 2024). "Tumor-promoting function of NPAS2 is dependent on HIF-1A activation and the engagement of glycolysis-related genes, indicating that NPAS2 may serve as an important therapeutic target to normalize glucose metabolic aberrations responsible for PCa progression." (PMID 36978001, 2023). "Collectively, these results demonstrated that NPAS2 could promote tumor growth of LUAD in vivo and function as an oncogene of LUAD." (PMID 37120564, 2023). "In cases in which the cancers are less luminal and more basal, shifting the biology of the tumor to a more luminal gene expression subtype by activating NPAS2 (and other required factors) could slow the growth of a basal tumors." (PMID 33858483, 2021). "The opposing effects of NPAS2 in cell cycle could be explained by the fact that the function of NPAS2 is tumor type specific." (PMID 28333141, 2017). "In addition, previous evidences have suggested that NPAS2 is a tumor suppressor that regulates different pathways, such as apoptosis, cell cycle determination, and DNA damage." (PMID 29285299, 2017). "Previous studies reported NPAS2 as a putative tumor suppressor." (PMID 28177907, 2017). "Moreover, BMAL1, another core clock transcription factor, was identified to heterodimerize with NPAS2 to bind to the E-box element in the promoter of CDC25A and be associated with the NPAS2-mediated tumor cell survival in HCC." (PMID 28333141, 2017). "Furthermore, beyond its implication in chronobiology, NPAS2 gene has also been suggested a transcriptional regulator and a putative tumor suppressor in breast cancer." (PMID 25989161, 2015). "Interestingly, NPAS2, one of the main circadian clock genes involved in DNA damage response mechanisms, has also been considered as a tumor suppressor gene and its alterations were already correlated with the tumor stage and metastases occurrence." (PMID 31151182, 2019). "In addition, functional analysis supports a tumor-promoting function for NPAS2 in HCC." (PMID 28333141, 2017). "Moreover, our data indicated that high expression of NPAS2 was significantly associated with high AFP and larger tumor size, implying that NPAS2 may have a tumor-promoting role in HCC." (PMID 28333141, 2017). "Taken together, our findings suggest that NPAS2 binds to and enhances the stability of H2AX mRNA, thereby decreasing the sensitivity of tumor cells to chemotherapy by augmenting DNA damage repair." (PMID 38291048, 2024). "The expressions of NPAS2, Ki67 and PCNA in tumor tissues of nude mice were tested by immunohistochemistry." (PMID 36978001, 2023). "As part of the ISG family, overexpression of NDC80, NPAS2, and AHNAK2 changed tumor microenvironment." (PMID 35813478, 2022). "Our findings demonstrate that NPAS2 has a critical role in HCC cell survival and tumor growth, which is mainly mediated by transcriptional upregulation of CDC25A." (PMID 28333141, 2017). "Circadian clock gene NPAS2 was initially described as a tumor suppressor gene but emerging evidence suggests a dual nature depending on the tumor type, while a role in GBM has not been described previously." (PMID 39796709, 2024). "Besides, the overlapping genes that exhibited similar expression levels in tumor samples from both the TCGA and ICGC databases were shown in a Venn diagram, including DBP, NPAS2, PER1, RORA, and TIMELESS." (PMID 34745328, 2021).